GATA3 (GATA binding protein 3)
Diseases named in the same sentence as GATA3 in open-access papers (continued):
Sharing a sentence is not in itself a finding about the gene and the disease.
breast carcinoma (continued). "To explore the possible regulation between these two genes, we silenced or overexpressed Notch3 or GATA-3 in breast cancer cells." (PMID 30100605, 2018). "Elevated GATA-3 expression in breast cancer cells leads to differentiation, and thereby suppression of tumor dissemination." (PMID 30100605, 2018). "GATA3 transcripts were 6.103 fold elevated in breast cancer samples as compared with normal tissues in a dataset with 593 samples that derived from TCGA (the Cancer Genome Atlas) database." (PMID 28423734, 2017). "Similar results were found in CCLE analysis, GATA3 over-expressed in the breast cancer cell lines with high level of ER expression, while under-expressed in those with low level or negative ESR1 expression (p<0.001)." (PMID 28423734, 2017). "We next evaluated the candidate genes in breast cancer, on which GATA3 also plays an important role according to the reports." (PMID 28415601, 2017). "Here, we performed a meta-analysis to explore determine the prognostic and clinicopathological value of GATA3 in breast cancer." (PMID 28394898, 2017). "Consistently, the expression level of miR-31 also negatively correlated to Gata3 and ERα levels in human breast cancer." (PMID 29051494, 2017). "The histopathology revealed a stromal adenocarcinoma, positive for GATA-3, pancytokeratin, and ER on IHC, suggesting breast cancer metastasis." (PMID 29344435, 2017). "GATA3 is a transcription factor for T cell development and a regulator of estrogen receptor in breast carcinoma." (PMID 28144859, 2017). "We developed a second model using CAMA1, another ER+ breast cancer cell line, which is GATA3 wild type." (PMID 29262572, 2017). "For example, GATA3 is strikingly high expressed in breast cancer, and the correlation between GATA3 expression and its enhancer methylation are significantly negative in both TCGA tumor set and validate dataset." (PMID 28621677, 2017). "Our meta-analysis suggests that GATA3 is a critical biomarker for predicting improved survival in breast cancer patients, which is the major finding of this study." (PMID 28394898, 2017). "The METABRIC study reported that GATA3 mutant tumors have a favorable prognosis compared to GATA3 wild type ER+ breast cancers." (PMID 29262572, 2017). "Recently a transcription factor GATA-binding protein 3 (GATA3) has been identified as a very sensitive marker for breast carcinoma, both in both primary and metastatic sites." (PMID 28693610, 2017). "The identified E2-responsible TRNs provide evidence that ESR1 form modulators with co-TFs or cofactors to regulate the downstream genes, especially with GATA3 to promote E2-inducd gene expression programs in breast cancer." (PMID 29051499, 2017). "The potential prognostic value of GATA binding protein 3 (GATA3) in breast cancer has recently increased, although the evidence is inconclusive." (PMID 28394898, 2017). "GATA3 was found to act upstream of FOXA1 in mediating ESR1 binding by analyzing ChIP-seq-binding signals in breast cancer cells." (PMID 29051499, 2017). "While GATA-3 expressions were also low in all the FRK-low breast cancer cells, with exception of MDA-kb2 and the HCC1419, likewise this was not limited to the FRK-low cells." (PMID 28077797, 2017). "GATA-binding protein 3 (GATA3) has been identified as a sensitive marker for breast carcinoma but its sensitivity in primary genital extramammary Paget diseases (EMPDs) has not been well studied." (PMID 28693610, 2017).
breast carcinoma (continued). "Our analysis validates ESR1 function as a main regulator linking cancer-related TFs, especially GATA3 to promote breast cancer development." (PMID 29051499, 2017). "In another dataset from Zhao's study, GATA3 was 3.806 fold elevated in breast cancer samples as compared with normal tissues (p=0.004)." (PMID 28423734, 2017). "GATA3 WT MCF-7 and CAMA1 cells grew poorly as xenografts in immunocompromised mice compared to GATA3 mutant cells, however, raising the possibility that GATA3 mutant breast cancer cells do depend on the mutant protein for tumor growth in vivo." (PMID 29262572, 2017). "And reviewed elsewhere, several other types of tumors including urothelial carcinoma, breast carcinoma, paragangliomas/pheochromocytomas, trophoblastic tumors, and mesonephric adenocarcinomas are often positive for GATA3." (PMID 28693610, 2017). "In summary, our findings have shown that IL-20 expression in breast cancer is regulated by a transcriptional complex composed of transcription factors, including ER(α), GATA3, and FOXA1, as well as a transcriptional elongation factor, Ell3." (PMID 28514748, 2017). "Even though GATA3 is so important to the mammary gland, how GATA3 influences survival of breast carcinoma patients remains an important question." (PMID 28394898, 2017). "As a pioneer factor for ER in breast cancer cells, the potent inhibition of GATA3 expression by CDK7 inhibitors provides further evidence for its potential utility in the treatment of ER-positive breast cancer." (PMID 27748765, 2017). "We identified genes with upregulated and downregulated expression in GATA3 mutant cells, a subset of which was concordantly differentially expressed in GATA3 mutant primary luminal breast cancers." (PMID 29262572, 2017). "This meta-analysis of 10 articles involving 5,080 breast cancer patients explored the prognostic and clinicopathological value of GATA3 in breast cancer." (PMID 28394898, 2017). "Expression of TBC1D9, a Rab GTPase accelerating protein, is highly correlated with ERα and Gata3 expression in human breast cancers." (PMID 29262572, 2017). "Researches have shown that ZEB2, TGFB1, MDM2 are important downstream effectors that can be inhibited by GATA3 in breast cancer." (PMID 28599307, 2017). "For instance, loss of Gata3 in adult mice leads to an expansion of undifferentiated luminal cells and basement-membrane detachment, which may promote tumor dissemination, while rescue of Gata3 expression reduces both tumorigenicity and metastatic potential of breast cancer cells." (PMID 28415601, 2017). "Here, we have utilized gene editing in human ER+ breast cancer cell lines to identify phenotypes and transcriptional targets dependent on mutant GATA3." (PMID 29262572, 2017). "That possibility is supported by our observations that FoxM1 inhibits expression of the differentiation genes GATA3 and FoxA1 in breast cancer cells." (PMID 28387346, 2017). "Immunohistochemical stains like GATA3 and cytokeratin should be employed in such cases, which have a sensitivity of 86% for breast cancer." (PMID 29344435, 2017). "In luminal breast cancer cells, GATA3 is known to functionally interact with the TFs FOXA1 and estrogen receptor-α, leading to the potential for GATA3 mutations to alter the transcriptional network of these factors." (PMID 26922637, 2016). "When encountering metastatic carcinoma that is positive for GATA3, the possibility of urothelial and breast carcinoma should be first considered." (PMID 27642214, 2016).
breast carcinoma (continued). "Utilizing our previous ChIP-seq data and ENCODE DNase-seq data, we confirmed the presence of a category of G3-like GATA3 bound sites in luminal breast cancer cells (T47D and MCF7 cells)." (PMID 26922637, 2016). "Recent studies show that GATA3 is exclusively expressed in ER-positive, well differentiated, early stage breast cancers." (PMID 27556500, 2016). "Consistent with the in vivo data, GATA3 exerts metastasis suppressive functions when expressed exogenously in a human basal-like breast cancer cell line by inducing the mesenchymal-to-epithelial transition (MET)." (PMID 26922637, 2016). "Mutations in GRIN2A, GATA3 and KDM6A which have been identified in melanoma, breast cancer and recently identified as a candidate driver of pancreatic carcinogenesis, respectively, were only identified within the EUS FNA cytology smear specimens." (PMID 27203738, 2016). "A representative example of this group is FOXC1, an important regulator of Basal-like breast cancer and a repressor of GATA3." (PMID 27539783, 2016). "Overexpression of GATA-2 was detected in a subset of human chronic myelogenous leukemia and human neuroblastoma samples, while GATA-3 was shown to be highly expressed in breast cancer, lymphoma and other tumors." (PMID 27528231, 2016). "GATA3 nucleates a transcription repression program to inhibit the invasive potential of breast cancer cells in vitro and to suppresses metastasis in vivo; it does this by targeting a cohort of genes, including ZEB2, which is critically involved in EMT." (PMID 27556500, 2016). "GATA3 downregulation has been observed in ER-negative breast cancersand has been described as a strong prognostic indicator of breast cancer." (PMID 26953528, 2016). "GATA3 is an immensely sensitive and relatively specific marker for urothelial as well as breast carcinoma." (PMID 27642214, 2016). "Because GATA3 has been proposed as a prognostic biomarker in breast cancer, the high frequency of GATA3 P409 and elevated GATA3 expression in BRCA make it a potential useful therapeutic target in clinics." (PMID 27356755, 2016). "These “repressed” genes include ESR1 (gene encoding ERα), ERBB2, GATA3, and ZNF217 —all critical genes to the etiology of breast cancer." (PMID 27539783, 2016). "Examining metastatic carcinoma with poorly differentiated and high-grade morphology and GATA3 expression, breast carcinoma including IPLC and poorly differentiated urothelial carcinoma are considered for the differential diagnosis." (PMID 27642214, 2016). "To investigate chromatin reprogramming during the MET process, we utilized MDA-MB-231 breast cancer cells, in which GATA3, and its known partners, FOXA1 and estrogen receptor-α, are below limits of detection at the protein level." (PMID 26922637, 2016). "We applied the MINDy (Modulator Inference by Network Dynamics) algorithm to four TFs (ESR1, FOXA1, GATA3 and SPDEF) that are key drivers of estrogen receptor-positive (ER+) breast cancer risk, as well as cancer progression." (PMID 27997592, 2016). "In this report, we provide detailed analysis of GATA3-mediated chromatin reprogramming in the context of MET in a system relevant to breast cancer; we observed several key outcomes." (PMID 26922637, 2016). "Suppression of ELK3 in another basal type breast cancer cell line, Hs578T, also accompanied with GATA3 activation as well as reduced migration and invasive capacity in vitro." (PMID 27556500, 2016). "In cultured breast cancer cells, GATA3 and ERα positively regulate each other's expression, forming a positive regulatory loop." (PMID 27374105, 2016). "The transcription factor FOXC1, an important biomarker of basal-like breast cancer, is a member of the anti-GATA3 group and is anticorrelated with GATA3 expression in TCGA data (Pearson's r = −0.602)." (PMID 27539783, 2016).
breast carcinoma (continued). "The expression of THSD4 is regulated by GATA3 and mediates transformation of normal cells into breast cancer through deregulation of THSD4." (PMID 27818681, 2016). "GATA3 and FOXA1 act as pioneer factors essential for mammary morphogenesis, and GATA3 is required for estradiol stimulation of cell cycle progression in breast cancer cells." (PMID 27833659, 2016). "In ER+ breast cancer cells, silencing of GATA3 inhibitedproliferation, suggesting a dependenceon GATA3 for maintained proliferation of ER+ cancer cells." (PMID 26884552, 2016). "ER,FOXA1 and GATA3 are three of the definingsignature genes consistently observed in ER+ breast cancers, and all three proteins have been shown to be required for theestablishment of an oestrogen-responsive ER complex." (PMID 26884552, 2016). "Most of our current knowledge regarding GATA3’s potential function in breast cancer has been revealed from genomic studies highlighting an ER/FOXA1/GATA3 co-operating network of transcription factors in luminal tumours and ER-positive cell line models." (PMID 27588951, 2016). "Here we explore the mechanistic basis by which GATA3 functions as a pioneer TF in a cellular reprogramming event relevant to breast cancer, the mesenchymal to epithelial transition (MET)." (PMID 26922637, 2016). "For example, in signal 1, rs812020 (per C-allele OR = 0.89, 95 % CI 0.87–0.91, P = 2 × 10-27) was annotated to a region bound by multiple key transcription factors for breast cancer, including GATA3 and FOXA1." (PMID 27459855, 2016). "We first established stable cell lines expressing wild-type GATA3 at levels comparable to that found in GATA3-positive breast cancer cells." (PMID 26922637, 2016). "Cytokeratin 7, estrogen receptors, and GATA3 immunohistochemistry disclosed the presence of numerous metastatic breast carcinoma cells infiltrating the splenic parenchyma." (PMID 27672468, 2016). "Our findings reveal important insights into mutant GATA3 function and breast cancer, provide the first potential therapeutic strategy and suggest that dual tumour suppressive and oncogenic activities are more widespread than previously appreciated." (PMID 27588951, 2016). "GATA3 localization following exogenous expression in MDA-MB-231 cells was compared to the pattern previously observed in the luminal epithelial breast cancer cell lines T47D and MCF7." (PMID 26922637, 2016). "Our data provide new experimental evidence that GATA3 functions as a pioneer factor during cellular reprogramming using the MET of breast cancer cells as a model." (PMID 26922637, 2016). "For instance, we found that GATA-containing enhancer hypomethylation occurred primarily in the subset of breast cancer cases belonging to the Luminal subtype, which also had high expression of the GATA3 gene." (PMID 25994056, 2015). "This is in line with previous report suggesting that decreased level of GATA3 correlates with higher E-cadherin and its overexpression inhibits metastasis in breast cancer." (PMID 26451614, 2015). "In the context of breast cancer, miR-29b has been recently identified as a part of a GATA3-miR-29b axis, which regulates the tumor microenvironment and inhibits metastasis." (PMID 25886595, 2015). "In agreement with cell line data, we found that PBX1 protein levels significantly correlate with ERα, FOXA1 and GATA3 (another important ERα pioneer factor) thus demonstrating that PBX1 is strongly associated with ERα-positive, luminal breast cancer subtypes." (PMID 26215677, 2015).
breast carcinoma (continued). "They confirmed the presence of mutations in driver genes previously implicated in breast cancer development, such as AKT1, BRCA1, CDH1 and GATA3." (PMID 26561834, 2015). "It would be interesting to investigate if H19 and MIR675 regulate the expression of the GATA3 gene, which is known to play a role in breast cancer development as well as the development and maturation of luminal cells in the mammary gland." (PMID 25944846, 2015). "Our previous and current works pivotally connect two critical regulatory axes, GATA3/miR29b and miR29b/AF1q/TCF7/CD44/KISS1, associated with the Wnt pathway for breast cancer metastasis." (PMID 26079538, 2015). "Gata3 has previously shown to over-express in ER+ patients, and it has also suggested to regulate genes critical to the hormone-responsive breast cancer phenotype." (PMID 25593195, 2015). "As expected, epithelial genes known to be inactivated during EMT in breast cancer cells, such as Cdh1 (E-cadherin), Ocln (Occludin), Epcam, Cldn7 (Claudin 7), Id1, Krt7, Esr1, Cav2, Dsp, Gata3, and Cadm1 were among the downregulated genes." (PMID 25674539, 2015). "In the case of breast cancer, ER, PR, GATA3, and mammaglobin can be helpful, while TTF1 and napsin-A can point toward lung adenocarcinoma." (PMID 26106499, 2015). "While GATA-3 is currently considered as a better marker for breast cancer, diffuse strong ER positivity and presence of GCDFP 15 are also suggestive of metastatic breast carcinoma." (PMID 26408025, 2015). "Most recently, a study further demonstrated that GATA3 suppresses breast cancer metastasis by inducing miR29b, which we have demonstrated to inhibit AF1q expression." (PMID 26079538, 2015). "On the more differentiated side of the mammary tumors, there was a significant decrease in luminal marker expression of Gata3, yet the levels of K8 and K18 remained unaffected." (PMID 26274893, 2015). "GATA3 participation in progestin-induced breast cancer growth was addressed in in vitro proliferation and in vivo tumor growth experiments." (PMID 25479686, 2014). "The zinc finger transcription factor GATA3 was first identified in the early 1990s and is considered to be a marker of luminal breast cancers." (PMID 24748983, 2014). "FOXA1 is co-expressed with ERα and GATA3 and appears to be related to the luminal subtype A in breast cancer." (PMID 24792166, 2014). "Combined, these analyses indicate that GATA3 levels are altered in both basal-like (decreased levels) and luminal (increased levels) breast cancers." (PMID 25410484, 2014). "To determine the signs of cross-regulatory connections between ERα and GATA3, we used siRNA to decrease either ERα or GATA3 protein synthesis and then examined the change in ERα and GATA3 protein levels in the ERα–positive T47D breast cancer cell line." (PMID 24792166, 2014). "The role of GATA3 in breast cancer as a tumor suppressor has been established, although insights into the mechanism of GATA3 expression loss are still required." (PMID 25479686, 2014). "To elucidate the contribution(s) of GATA3 alterations to cancer, we studied two breast cancer cell lines, MCF7, which carries a heterozygous frameshift mutation in the second zinc finger of GATA3, and T47D, wild-type at this locus." (PMID 24758297, 2014). "Concordantly, ectopic expression of GATA3 in basal-like breast cancer cell lines suppresses their metastatic potential and alters the tumor microenvironment." (PMID 24792166, 2014). "Both molecular mechanisms converge to accomplish decreased GATA3 expression levels in breast cancer cells upon PR activation." (PMID 25479686, 2014). "In this study, we demonstrate that progestin-activated progesterone receptor (PR) reduces GATA3 expression through regulation at the transcriptional and post-translational levels in breast cancer cells." (PMID 25479686, 2014).